IL1B (interleukin 1 beta)
Diseases named in the same sentence as IL1B in open-access papers (continued):
Sharing a sentence is not in itself a finding about the gene and the disease.
ischemic stroke (continued). "LED therapy also downregulated the expression of proinflammatory cytokines IL-18 and IL-1β and attenuated the NLRP3 inflammasome in an ischemic stroke model." (PMID 31287006, 2019). "TAOK1 expression was significantly down-regulated, however, IL-1β, IL-6 and IL-8 expression were up-regulated in MCAO rat model and OGD-induced neural stem cell model of ischemic stroke." (PMID 31652447, 2019). "In line with the previous studies, ischemic stroke induced massive production of TNF-α, IL-1β, and IL-6." (PMID 29544517, 2018). "Both in vivo and in vitro ischemic stroke models induced the production of inflammatory mediators, including TNF-α, IL-1β, iNOS, and IL-10." (PMID 28592261, 2017). "BBG, a P2X7R antagonist, can reduce MCAO/R injury-induced microglial microvesicle-like components, IL-1β expression, glial activation and delayed neuronal death in hippocampal CA1 region after ischemic stroke." (PMID 29017492, 2017). "For example, apelin significantly reduces the expression of inflammatory cytokines in rat brains, such as interleukin 1 beta (IL-1β), TNF-α and intercellular adhesion molecule 1(ICAM-1), and inhibits cell apoptosis in rats with ischemic stroke." (PMID 28167898, 2017). "Attenuation of CX3CL1 signaling by CX3CL1 or CX3CR1 gene knockdown both significantly reduced infarct size, expression of IL-1β and TNF-α, and leukocyte infiltration in ischemic stroke models." (PMID 26860080, 2016). "We demonstrated that estradiol possessed anti‐inflammatory effects including suppressing the serum concentration of IL‐1β and TNF‐α after ischemic stroke in vivo and also in primary microglia culture." (PMID 27127723, 2016). "Interleukin-6 (IL-6) interleukin-1 beta (IL-1b), and tumor necrosis factor-alpha (TNF-α) are one of the important atherogenic markers in ischemic stroke patients." (PMID 26075263, 2015). "IL-1β and TNF-α, the major YKL-40 inducer cytokines, are synthesized from microglia and macrophages in penumbra after ischemic stroke." (PMID 23272150, 2012). "IL-1β expression, like TNF-α, seems to promote infarction progression in animal models of ischemic stroke." (PMID 22082476, 2011). "The present study found elevated IL-1β, IL-6 and TNF-α level in CSF at the sixth hour from ischemic stroke onset." (PMID 21450100, 2011). "The objective of the present study was to provide additional insight into the cell types and cell subpopulations that produce IL-1β and TNF-α within the first 24 hours following ischemic stroke in mice." (PMID 18947400, 2008). "Interleukin-1β (IL-1β) and tumor necrosis factor-α (TNF-α) are expressed by microglia and infiltrating macrophages following ischemic stroke." (PMID 18947400, 2008). "Taken together, the results show that IL-1β and TNF-α are produced by largely segregated populations of microglia and macrophages after ischemic stroke in mice." (PMID 18947400, 2008). "Previous studies have demonstrated that newly repopulated microglia had reduced expression of inflammatory markers (e.g., IL-1β, IL-6, TNF-α and CD86), and upregulation of neuroprotective factors (e.g., CD206, TGF-β, and IL-10) in response to ICH ischemic stroke in ageing." (PMID 40777042, 2025). "In a rat ischemic stroke model, it inhibited the stimulation of microglia and astrocytes and decreased the expression of TNF-α, IL-1β, ıntercellular adhesion molecule (ICAM)-1, vascular cell adhesion molecule (VCAM)-1, inducible NO synthase (iNOS), and aquaporin-427." (PMID 40498951, 2025). "We found significantly higher levels of salivary pro-inflammatory cytokines (IL-1β, TNF-α, TNF-β), anti-inflammatory cytokines (IL-1ra, TRAIL), Th1 cytokines (IFN-γ and IL-12 (p40)), and Th2 cytokines (IL-6) in patients with ischemic stroke compared to healthy participants." (PMID 40520895, 2025). "To investigate whether GJC-CDs are involved in the inflammatory response in ischemic stroke, we examined the levels of TNF-α, IL-1β, IL-6, and IL-10 in the serum of each group of mice." (PMID 40573265, 2025).
ischemic stroke (continued). "In addition to major cytokines like IL-1β, IL-6, TNF-α, and IL-10, several other inflammatory mediators play significant roles in ischemic stroke." (PMID 40869247, 2025). "However, following ischemic stroke, astrocytes and microglia become mutually activated and release pro-inflammatory cytokines such as TNF-α and IL-1β." (PMID 41035004, 2025). "Therefore, therapeutic electrical stimulations modulated the decrease in inflammatory cytokines, including IL-1β and TNF-α, in the ischemic stroke mice model by activating the STAT1 and NF-kB signaling pathways." (PMID 39062789, 2024). "Likewise, increased plasma levels of IL-1β, IL-6, and TNF-α have been reported in ischemic stroke patients." (PMID 36536168, 2024). "The GMDR analysis revealed that the combination of MPO-DNA, AIM2, and IL-1β exert a synergistic effect on the prognosis of LAA stroke, which indicated NETs/AIM2/IL-1β axis may involve in inflammatory damage after ischemic stroke." (PMID 39737165, 2024). "After ischemic stroke, TREM2-KO mice exhibit reduced microglial activity, with decreased transcription of pro-inflammatory cytokines TNFα, IL-1α, and IL-1β, as well as reduced transcription of chemokines CCL2 (MCP1), CCL3 (MIP1α), and chemokine receptor CX3CR1." (PMID 39649720, 2024). "Yet, bone marrow–derived MDCs also express a core inflammatory gene signature following ischaemic stroke, through the induction of type I interferon (IFN), inducible nitric oxide synthase (iNOS), IL-1β, and IL-6 genes and retain capacity to produce IL-1β and tumour necrosis factor (TNF)α ex vivo." (PMID 36346451, 2023). "In the wake of ischemic stroke, increased DAMPs from injury cells and stimulated NLRP3 protein bind to the adapter protein ASC and pro-caspase-1, subsequently triggering the maturation of precursors IL-1β and IL-18 to induce neuroinflammation." (PMID 37915409, 2023). "Moreover, the KEGG Mapper results further showed that IL-1β, TNF-α, IL-6, and IL-4 are core potential targets involved in Epimedium-mediated neuroinflammation following ischemic stroke." (PMID 36338345, 2022). "The same frequency interval (1–20 Hz) may reduce the levels of pro-inflammatory cytokines, including IL-1b, IL-6, and TNF-α, in rats following ischemic stroke." (PMID 35055089, 2022). "For example, recent studies have documented how mir-223 may represent a new therapeutic expedient in case of ischemic stroke as it binds to a conserved site in the 3 UTR of the NLRP3, inactivates the latter, and inhibits the release of IL-1β." (PMID 36297283, 2022). "In addition, ELISA showed that levels of pro‐inflammatory factors (IL‐1β, IL‐6, TNF‐α) were increased after ischemic stroke." (PMID 35695696, 2022). "Considering that both caspase‐1 and IL‐1β are key components of the AIM2 inflammasome, we hypothesized that AIM2 plays a crucial role in mediating BBB integrity after ischemic stroke." (PMID 34156153, 2021). "It has been shown that IL‐1β is one of the major inflammatory factors that induces ischemic brain injury, which increases BBB permeability, neuron death, and even the transformation of cerebral hemorrhage in ischemic stroke." (PMID 32529750, 2020). "What is more, it was also reported that MCC950 improved neurological dysfunction at 24 h after cerebral I/R and promoted 28-day survival rate in diabetic mice with ischemic stroke, involving in the mRNA transcription level changes of NLRP3, caspase-1, and IL-1β." (PMID 32581721, 2020). "Indeed, blocking Kv1.3 with PAP‐1 reduced microglia activation and overall brain levels of the inflammatory cytokines IL‐1β and IFN‐γ, leading to smaller infarct areas and improved neurological deficit scores in a mouse model of ischemic stroke." (PMID 32525239, 2020). "In addition, we compared blood levels of IL-1α, IL-1β, IL-1Ra, TNF, TNFR1, and TNFR2 in samples from ischemic stroke survivors and healthy controls." (PMID 32503645, 2020).
ischemic stroke (continued). "In addition, EA treatment inhibits microglia-mediated neuroinflammation through inactivation of p38 MAPK and MyD88, accompanied by the decrease of IL-1β, IL-6, and TNF-α after ischemic stroke." (PMID 31866829, 2019). "We found that experimental ischemic stroke caused significant BALF inflammation (increase in macrophages and neutrophils) and an increase in whole-lung pro-inflammatory cytokines (IL-1β) but did not result in ALI and ARDS." (PMID 30842652, 2019). "Ischemic stroke caused a significant increase in bronchoalveolar lavage fluid (BALF) macrophages and neutrophils and whole lung tissue proinflammatory IL-1β mRNA expression but this did not translate into histologically evident ALI." (PMID 30842652, 2019). "Ischaemic stroke induced massive production of TNF‐α, IL‐1β and IL‐6 in Iba‐1+ cells." (PMID 31087489, 2019). "In an ischemic stroke rat model, IL-1α, but not IL-1β, was expressed early on microglia-like cells in the ischemic hemisphere." (PMID 31554320, 2019). "The MCAO challenge itself induced a significant up-regulation of pro- and anti-inflammatory genes in the brains of both control and treatment animals, including IL-6, IL-1β, TNF-α, IL-10, CCL2, and CCL3, indicating a pivotal role of neuroinflammation in the pathology of acute ischemic stroke events." (PMID 30126083, 2018). "We investigated whether IL-1β and TNF-α are synthesized by overlapping or segregated populations of cells after ischemic stroke in mice." (PMID 18947400, 2008). "The relative physiological outcome of increased IL-1β and TNF-α signaling in ischemic stroke may depend on the kinetics and location of cytokine producing cells." (PMID 18947400, 2008). "Interestingly, in acute MI and ischemic stroke, the expression of APAF1 and IRAK3 was negatively correlated with the abundance of NK cells, while the expression of ATM, CAPN1, IL1B, IL1R1, PRKACA, PRKACB and TNFRSF1A was positively correlated with the abundance of NK cells in MI." (PMID 38526027, 2024). "Epimedium treatment significantly inhibited the expression of IL-1β, TNF-α, and IL-6 and enhanced the expression of IL-4, which suggests that Epimedium exerted its neuroprotective effects via regulating the expression of proinflammatory and anti-inflammatory cytokine following ischemic stroke." (PMID 36338345, 2022). "Besides, ruscogenin is a crucial steroid sapogenin derived from Ophiopogn japonicus, and ruscogenin could improve neurological dysfunctions of ischemic stroke mice via suppressing expression levels of NLRP3, IL-1β, caspase-1, TXNIP, MAPK, and ROS." (PMID 32581721, 2020). "Furthermore, it is presently unknown whether IL-1β and TNF-α are expressed to the same extent by the same or different subsets of microglia and macrophages following ischemic stroke." (PMID 18947400, 2008). "When an ischemic stroke occurs, the lack of α9 in neutrophils limits the inflammatory response by lowering TNF-α, IL-1β, and IL-6 levels." (PMID 39649720, 2024). "We have shown for the first time that IL-1β and TNF-α are produced by largely non-overlapping subsets of microglia and macrophages after induction of ischemic stroke in mice." (PMID 18947400, 2008). "In ischemic stroke patients, we demonstrate that plasma TNFR1 and TNFR2 levels increased in the acute phase after symptom onset compared to healthy controls, whereas TNF, IL-1α, IL-1β, and IL-1Ra did not change." (PMID 32503645, 2020). "Finally, plasma TNFR1 and TNFR2 levels increased significantly in the acute phase after symptom onset in ischemic stroke patients compared to healthy controls whereas TNF, IL-1α, IL-1β, and IL-1Ra did not change." (PMID 32503645, 2020).
Cerebral ischemia (247 papers, 2006 to 2025). Restriction of arterial blood supply to the brain associated with insufficient oxygenation to support the metabolic requirements of the tissue. "The proinflammatory cytokine IL-1β is associated with neurodegenerative diseases caused by excitotoxic or traumatic injury, most notably in experimental cerebral ischemia in rodents." (PMID 39762792, 2025). "Excessive ROS following cerebral ischemia/reperfusion not only directly cause cell injury but also activate numerous inflammatory cytokines, including IL-6 and IL-1β, which are released rapidly." (PMID 40527853, 2025). "Cerebral ischemia-induced endothelial dysfunction has also been associated with proinflammatory milieu and increased oxidative stress, increased IL-1β and cyclooxygenase products, and alterations in circulating white blood cells." (PMID 39311310, 2024). "Modern research shows that NF-κB is activated, leading to the excessive production of proinflammatory cytokines, including TNF-α, IL-1β, and IL-6, and inducible nitric oxide synthase, which cause inflammatory injury on the basis of cerebral ischemia." (PMID 35463086, 2022). "Cerebral ischemia is followed by an inflammatory reaction, the release of various proinflammatory cytokines, including IL-6, IL-1β and TNF-α, is the main mechanism underlying ischemic inflammatory injury." (PMID 32518214, 2020). "Following cerebral ischemia and reperfusion, many proinflammatory and cytotoxic factors, including IL-6, IL-1β, TNF-α, and NO, can cause cell injury and apoptosis." (PMID 30949500, 2019). "Microglia/macrophage activation, together with elevated expression of pro-inflammatory cytokines such as IKK-β, NF-kB, TNF-α, and IL-1β, demonstrated that the warfarin-associated HT induced a neuroinflammation after cerebral ischemia." (PMID 27566245, 2016). "In particular, increased IL-1β, IL-6, and TNFα concentrations were linked to a poor prognosis in infants suffering from ischemic encephalopathy." (PMID 27565558, 2016). "Occlusion of the middle cerebral artery (MCAO), which causes cerebral ischemia in mice, induced expression of IL-1β in the brains of both wild-type and MK2−/− mice, but IL-1β levels were significantly lower in MK2-deficient animals." (PMID 24705157, 2013). "Consistent with the well established induction of pro-inflammatory cytokines by cerebral ischemia, HI produced a marked elevation of mRNAs encoding TNFα, IL-1β and IL-6 (Veh-HI)." (PMID 23251498, 2012). "Here, we report that MCP-1-deficiency impairs the induction of IL-6, IL-1β and partially G-CSF early after cerebral ischemia, resulting in a reduced influx of neutrophil granulocytes and T-cells." (PMID 22031820, 2011). "Rutaecarpine (MOL002662) can inhibit the production of pro-inflammatory factors IL6 and IL1B, thereby reducing the inflammatory response and oxidative stress caused by cerebral ischemia–reperfusion (CI/R) and increasing the levels of anti-inflammatory factors and superoxide dismutase." (PMID 33681222, 2021). "Cerebral ischemia and reperfusion injury result from the rapid and explosive reoxygenation induced by the inflammatory response, which is tightly associated with inflammatory mediators such as IL-1β, TNF-α, and IL-6." (PMID 29867706, 2018). "Particularly, IL-1β is closely associated with the pathogenesis of cerebral ischemia." (PMID 28491108, 2017). "IL-1β has been clearly implicated in the pathogenesis of cerebral ischemia." (PMID 27703487, 2016). "In cerebral ischemia, brain vascular endothelial cells have been implicated as a primary source of IL-1β, but extensive evidence indicates that the initial cellular source of IL-1β in response to CNS injuries is activated microglia with subsequent upregulation of the cytokine in macroglia." (PMID 22615852, 2012).
Cerebral ischemia (continued). "Our results show that lack of MCP-1 impairs IL-1β expression especially within the ischemic core 12 hours after onset of cerebral ischemia, which is in agreement with findings of previous studies demonstrating a causal relationship between diminished IL-1β and smaller infarct sizes." (PMID 22031820, 2011). "In the present study, the heat stroke-induced increases in arterial hypotension, cerebral ischemia and neuronal damage are associated with elevated levels of DA, 5-HT, glutamate and hydroxyl radicals in rat brain, and increased circulating IL-1β, TNF-α and MDA in the peripheral blood stream." (PMID 20937119, 2010). "Some studies have shown that when the NLRP3 inflammasome is activated, it releases downstream pro-inflammatory mediators such as IL-1β and IL-18, which become one of the key factors triggering neuroinflammation after cerebral ischemia–reperfusion." (PMID 39926015, 2025). "The TLR4/IL-1β/NF-кβ signaling pathway has been reported to play a role in various CNS conditions, such as cerebral ischemia and traumatic brain injury." (PMID 40153412, 2025). "Corroborating these insights, our research unveiled heightened TNF-α, IL-1β, and IL-6 concentrations in hippocampal and prefrontal cortical tissues post-cerebral ischemia." (PMID 40144659, 2025). "It was found that the expression of inflammatory factors (TNF-α, IL-1β, and IL-6) in neutrophils after cerebral ischemia or reperfusion was significantly reduced in mice with deletion of the PKM2 gene in myeloid cells." (PMID 39926015, 2025). "Simultaneously, enhance brain ischemia/subarachnoid hemorrhage injury, decrease neuroinflammation, limit astrocyte and microglia activation, and lower IL-1β levels." (PMID 41383474, 2025). "In the Western blot and immunofluorescence analyses, the expression levels of pyroptosis-related factors, such as NF-κB, NLRP3, GSDMD, ASC, Caspase-1, and IL-1β, were increased significantly after cerebral ischemia-reperfusion injury." (PMID 39199474, 2024). "In the presence of cerebral ischemia, activated cells (including neurons, astrocytes, and endothelial cells) release pro-inflammatory cytokines such as IL-1β, IL-6, and IL-18, which induce the death of neurons and glial cells." (PMID 38601463, 2024). "In cerebral ischemia animal models, the IL-1β mRNA expression spiked within minutes of ischemia onset, and its protein expression surged 4–6 h later." (PMID 38671959, 2024). "We also identified significant increases in NF-κB, TNF-α, and IL-1β in cerebral ischemia, and retinoic acid significantly alleviated these increases." (PMID 38527023, 2024). "Cerebral ischemia resulted in significantly increased levels of IL-1β, IL-6, and TNF-α compared with those after sham treatment." (PMID 37812268, 2024). "A previous study found that isoflurane exposure downregulated the pro‐inflammatory factors (such as IL‐18 and IL‐1β) in rats suffering from cerebral ischemia–reperfusion injury, and improved neuroinflammation and cognitive function." (PMID 38945806, 2024). "This study established the first evidence of Mxene-bpV’sneuroprotective effects against cerebral ischemia-reperfusion injury via a reduction in the levels of pro-inflammatory cytokines, including IL-1β, IL-6 and TNF-α." (PMID 39073469, 2024). "Phospholipase A2 of PRDX6 can improve cerebral ischemia/reperfusion inflammatory injury by reducing the expression of the inflammatory cytokines IL-1β, IL-17, and IL-23 and oxidative stress." (PMID 38360841, 2024). "In the early stage of ischemic brain injury disease, cerebral ischemia/reperfusion injury induces macrophages to secrete IL-1β and TNF-α, activate white blood cells, and generate inflammatory response." (PMID 38927572, 2024). "Following cerebral ischemia, inflammatory processes are initiated, with microglia and astrocytes releasing pro-inflammatory cytokines like IL-1β, TNF-α, and IL-6." (PMID 39625909, 2024).